PCM1 (pericentriolar material 1)
Diseases named in the same sentence as PCM1 in open-access papers (continued):
Sharing a sentence is not in itself a finding about the gene and the disease.
Obesity (2 papers, 2021 to 2022). Accumulation of substantial excess body fat. "The PCM1 gene, which was reported to associate with early‐onset obesity in children, caught our attention." (PMID 35386394, 2022). "Furthermore, the results illustrate that the mRNA expression levels of PCM1, SIRT1, EEF1G, PTEN and RPS2 were significantly decreased in the obesity compared with the control group." (PMID 34248836, 2021).
ZIKV infection (2 papers, 2022 to 2025). "Therefore, we hypothesize that ZIKV infection induces Mib1-mediated proteasomal activity to degrade PCM1 and Cx43 and damage the gap junction, and also impairs lamin A, hence impairing syncytia function of cardiomyocytes." (PMID 36226984, 2022).
acute leukemia (1 paper, 2014). A clonal (malignant) hematopoietic disorder with an acute onset, affecting the bone marrow and the peripheral blood. "A fusion of PCM1 and JAK2 is a recurrent abnormality in chronic and acute leukemia." (PMID 25148247, 2014).
asthenospermia (1 paper, 2025). "In contrast, deficiency of the less conserved satellite protein PCM1 only resulted in asthenospermia and partial sperm head deformity but did not affect sperm flagellum biogenesis." (PMID 40585997, 2025). "Contrarily, knockout of Pcm1 only results in asthenospermia and partial deformity of the sperm head without affecting the formation of the sperm flagellum." (PMID 40585997, 2025).
Ataxia (1 paper, 2023). Ataxia refers to impaired coordination of voluntary muscle movement. "Consistent with altered cerebellar function, Pcm1−/− mice displayed ataxia." (PMID 36790165, 2023).
Auditory hallucination (1 paper, 2025). Perception of sounds without auditory stimulus. "Another gene associated with auditory hallucinations is PCM1, which encodes a protein that forms a complex with other members of the DISC1 interactome, including BBS4 and DISC1." (PMID 40943654, 2025). "We observed an association between Neuregulin 1 (NRG1) and auditory hallucinations in patients with psychosis (p = 5.25 × 10−6, Z = 4.40), as well as between the gene encoding pericentriolar material 1 (PCM1) and auditory hallucinations (p = 4.47 × 10−4, Z = 3.32)." (PMID 40943654, 2025).
cardiac arrest (1 paper, 2024). Cessation of breathing and/or cardiac function. "Ki67 showed a similar pattern, where rare Ki67+/PCM1+ cells were found in the AVj after cardiac arrest (Fig. 4c1–c4)." (PMID 38902373, 2024). "The physiological significance of the increased number of twin-nuclei as well as the Ki67+/PCM1+ and PCNA+/PCM1+ nuclei in and the remodelling cardiomyocytes after cardiac arrest thus needs further investigation." (PMID 38902373, 2024). "Furthermore, co-expression of PCNA and Ki67 with PCM1 was only found in the cardiac arrest group in the AVj." (PMID 38902373, 2024). "However, co-expression of PCNA and PCM1 in cardiomyocyte nuclei was found only in the cardiac arrest group (Fig. 4a1–a3)." (PMID 38902373, 2024).
cognitive decline (1 paper, 2020). "PCM1 LOF may represent such a scenario relevant to that model of cognitive decline, as the phenotypes present later in life." (PMID 33214552, 2020).
Hydrocephalus (1 paper, 2023). Hydrocephalus is an active distension of the ventricular system of the brain resulting from inadequate passage of CSF from its point of production within the cerebral ventricles to its point of absorption into the systemic circulation. "We found that, in the absence of PCM1, ependymal cells displayed retarded centriole amplification and multiciliogenesis, as well as hydrocephaly." (PMID 36790165, 2023).
leukocytosis (1 paper, 2023). "All 8 patients with JAK2 fusion genes (PCM1, n = 7; BCR, n = 1; male 7/8; median age 69 years, range 29–73) presented with leukocytosis (median 25.9 × 109/l, range 10.5–55.0)." (PMID 37454239, 2023).
myocardial infarction (1 paper, 2021). Gross necrosis of the myocardium, as a result of interruption of the blood supply to the area, as in coronary thrombosis. "Here, we obtained transcriptomes of PCM-1-sorted mouse cardiomyocyte nuclei of healthy left ventricle and 7 days post myocardial infarction border zone tissue." (PMID 34821687, 2021).
osteosarcoma (1 paper, 2015). A usually aggressive malignant bone-forming mesenchymal neoplasm, predominantly affecting adolescents and young adults. "In agreement with our previous findings, ultraviolet irradiation of human U2OS osteosarcoma cells led to a quantitative loss of CEP131, PCM1 and SSX2IP from CS in a p38-dependent manner." (PMID 26616734, 2015).
prostate tumors (1 paper, 2016). "For example, we note that ~15% of prostate tumors exhibit deletions in the PCM1 gene (cBioPortal)." (PMID 27146717, 2016).
psychosis (1 paper, 2025). "Suppression of these genes disrupts neuronal migration, and mutations in PCM1 have been reported in families affected by psychosis." (PMID 40943654, 2025).
pulmonary fibrosis (1 paper, 2023). Chronic progressive interstitial lung disorder characterized by the replacement of the lung tissue by connective tissue, leading to progressive dyspnea, respiratory failure, or right heart failure. "Deficiency in O‐GlcNAcylation disperses PCM1 and CEP131, impairs the connections between microtubules and the centrosome, and disturbs cell polarity, which could be an underlying mechanism of pulmonary fibrosis." (PMID 37963851, 2023).
rectal cancer (1 paper, 2022). A primary or metastatic malignant neoplasm that affects the rectum. "Non targeted novel fusions were also identified including FGFR1-NRG1 in breast, BRAF-MRPS33 in prostate, SND1-MET in lung, PCM1-BRAF in sarcoma and TMEM178B-MET in rectal cancer." (PMID 35984852, 2022).
cancer (21 papers, 2005 to 2026). A tumor composed of atypical neoplastic, often pleomorphic cells that invade other tissues. "The human PCM1 has been implicated in several forms of cancer and neuropsychiatric disorders, but the in vivo dynamics and function of PCM1 in mitotic progenitors are unclear." (PMID 41315244, 2025). "Therefore, PCM1 dysfunction has a remarkable impact on cell physiology and is associated with both primary cilium-related diseases and cancer." (PMID 39595195, 2024). "Here, we identified a novel gene panel, PCM1, that can be utilized to evaluate cancer-related expression patterns in HBV-infected livers." (PMID 36829466, 2023). "Yet, this patient also showed a VUS with a high score for pathogenic prediction in the RBL1 gene and a truncating VUS in the PCM1 gene, which are both cancer-related genes." (PMID 36077770, 2022). "The other five genes: RECQL4, MYCL1, KDM5C, NUMA1, and PCM1 are documented in the cancer Gene Census list." (PMID 26998479, 2015). "This means that variants in genes only infrequently altered in cancer but which are nonetheless highly useful in diagnosis (e.g. PHF6/PCM1 in case 9, NONO in case 45), can be picked up." (PMID 38997407, 2024). "Common CNLs negatively influencing DFS and cancer-specific OS harboured the feline orthologous of multiple HBC-related genes reported as commonly deleted including FOXP1, FBXO25, CSMD1, AGPAT5, PCM1, PTPRG, and PDGFRL15,19,27,28,41–43." (PMID 31969654, 2020). "In cancer cells, Sld5 depletion dispersed PCM1, AZI1, and CEP290-positive centriolar satellites without eliminating these satellite proteins, reduced dynein heavy chain expression, and destabilized dynein-dynactin localization at spindle poles." (PMID 42182163, 2026). "For example, expression of CENPJ, PCM1 and CEP55, which are key centromere proteins, has been observed to promote cell proliferation and migration, and may even modulate treatment response for cancer." (PMID 39565278, 2025). "Importantly, the q-arm carries several cancer-relevant genes such as FGFR1, KAT6A and PCM1." (PMID 34707142, 2021).
tumor (14 papers, 2007 to 2025). "Specifically, these mutations are located on five tumor suppressors (SDHA, RB1CC1, PTCH1, DMBT1, BCR) and eight proto-oncogenes (MERTK, CSF1R, MYB, ROS1, PCM1, FGFR2, MYH11, BRCC3) and have an allele frequency lower than 0.01 in the Genome Aggregation Database (GnomAD)." (PMID 33466296, 2021). "Several candidate tumor suppressor genes have been identified from 8p including DLC-1 (8p21.3-22), FEZ1 (8p22), liver-related putative tumor suppressor (LTPS) gene (8p23), PCM1(encoding a centrosomal protein) and DUSP4/MKP-2 (encoding a MAP kinase phosphatase)." (PMID 17784942, 2007). "Among the PCM1 genes, AKRB10 showed the highest difference between tumor and normal, with a mean H score in normal smaller than one, while mean the H score in tumors was 185.8." (PMID 36829466, 2023). "Our finding that the majority of the differentially expressed PCM1 genes between HCC tumor and normal are higher in HCC tumors also suggests that the PCM1 signature identifies HCC-specific expression patterns." (PMID 36829466, 2023). "As well as in EESCC, cell cycle (e.g., PCM1, LIG1, etc.)and glycolysis (e.g., PGK2, ENO3, etc.)were predominant in the tumor tissues of EDAC." (PMID 35397555, 2022).
hematologic malignancies (3 papers, 2013 to 2019). "Further genes simultaneously affected by sCNAs and SNVs/indels, included POT1, JAK1, and PCM1, which are all linked to hematologic malignancies." (PMID 29449575, 2018).
infection (1 paper, 2013). The state of being infected such as from the introduction of a foreign agent such as serum, vaccine, antigenic substance or organism. "Some of them showed an amplification of the differential regulation during the time-course of WNV-infection (early vs. mock and late vs. early), such as PPID and PCM1 (down-regulated) and TAPBP and STAT1 (up-regulated)." (PMID 23874584, 2013).
neurodevelopmental disorder (1 paper, 2017). A behavioral and cognitive disorder with onset during the developmental period that involves impaired or aberrant development of intellectual, motor, or social functions. "It is unknown, however, whether PCNT, Disc1, and PCM-1, act independently or in an orchestrated manner in neurodevelopmental disorders." (PMID 28125008, 2017).
psychiatric disorder (1 paper, 2020). A disorder characterized by behavioral and/or psychological abnormalities, often accompanied by physical symptoms. "We quantified WT and Pcm1−/− littermates’ prepulse inhibition (PPI), a test for sensorimotor gating which is abnormal in SZ as well as in several other psychiatric disorders." (PMID 33214552, 2020).
PCM1 also shares sentences with these, for which no sentence is quoted: Huntington disease (2 papers); myeloid neoplasm (2); papillary thyroid carcinoma (2); Polycythemia Vera (2); primary myelofibrosis (2); retinal degeneration (2); acute myeloid leukemia (1); astrocytomas (1); autism (1); Autoimmunity (1); brain injury (1); brain tumor (1); chronic lymphocytic leukaemia (1); chronic myelomonocytic leukemia (1); CNS tumors (1); Cognitive impairment (1); colorectal cancer (1); colorectal tumors (1); dwarfism (1); dyslexia (1); epilepsy (1); essential thrombocythemia (1); heart failure (1); hepatocellular carcinoma (1); HIV-1 infection (1); Hypothermia (1); influenza infection (1); liver fibrosis (1); lymph node metastasis (1); lymphoma (1).
A further 11 diseases each share a sentence with PCM1 in 1 paper.